PPARA (peroxisome proliferator activated receptor alpha)
Diseases named in the same sentence as PPARA in open-access papers (continued):
Sharing a sentence is not in itself a finding about the gene and the disease.
Obesity (continued). "The metabolic changes associated to the activity of PPARα may depend on the stage of obesity and diabetes." (PMID 24261558, 2013). "The objective of this study was to investigate whether concurrent activation of LXR/PPARα can produce synergistic benefits in treating obesity-associated metabolic disorders." (PMID 23762402, 2013). "The miR-519d-dependent decrease in PPARα translation was further shown to increase lipid accumulation during pre-adipocyte differentiation suggesting that PPARα loss through miR-519d overexpression importantly contributed to adipocytes hypertrophy observed with obesity." (PMID 23024649, 2012). "Similarly to PPARγ, it is possible that PPARα activity also modulates obesity associated inflammation either through its metabolic activity or anti-inflammatory effects." (PMID 21382489, 2011). "Similarly to PPARα deficiency, PPARγ deficiency in adiposetissue (PPARγ-adiposeKO) was reported to protect from obesity andinsulin resistance caused by HFD." (PMID 17389764, 2007). "Additionally, they can elevate the risk of obesity in children and adolescents by activating PPARγ (peroxisome proliferator-activated receptor gamma) and PPARα (peroxisome proliferator-activated receptor alpha), pivotal factors in lipid and glycogen metabolism." (PMID 40066031, 2025). "Although PPARα did not feature as a key molecule in our pathway analyses, recent studies carried out in the liver suggest that Ago2 function is intrinsically associated with PPARα and, consequently, with mitochondrial energy metabolism that may contribute to obesity-associated pathophysiology." (PMID 34716428, 2022). "The advantage of dual PPARα/δ agonist with respect to renal function was demonstrated by a lower risk of serum creatinine elevation with elafibranor (PPARα/δ agonist) user than fenofibrate (PPARα agonist, 7.1% versus 17.2%) user with obesity and steatohepatitis." (PMID 31321239, 2019). "Among the three isoforms of PPARs (PPARα, PPARβ/δ, and PPARγ), PPARα plays an important role in the regulation of fatty acid oxidation and lipid metabolism and is beneficial for its protection against metabolic disorders associated with type 2 diabetes and obesity." (PMID 26225954, 2015). "For example, leucine supplementation prevents obesity in rodents and is associated with lower adiposity in humans, while isoleucine was shown to decrease tissue triglyceride accumulation and adiposity and increase expression of PPARα and uncoupling proteins in mice." (PMID 25505420, 2014). "Although the main interest in PPAR-related studies has been focused on the role of PPARs in energy homeostasis, PPARs, especially PPARα and PPARγ, are also shown to be involved in the regulation of the immune and inflammatory responses in obesity-linked diseases." (PMID 23594962, 2013). "Thus, while evidence is mounting that PPARα activationreduces adipose inflammation as observed during obesity, it isunclear whether the anti-inflammatory effects of PPARα inWAT are caused by direct or indirect mechanisms." (PMID 17389767, 2007). "Elevated palmitic acid (PA) levels in obesity suppress PPARα via miR548ab release, thereby impairing the PPARα-HACL1-C19:0 signaling pathway." (PMID 41738141, 2026). "In contrast, obesity or consumption of a high-fat diet leads to decreased levels of bilirubin and PPARα, resulting in elevated FAS (fatty acid synthase) and ACC (acetyl-CoA carboxylase) expression, which promotes triglyceride accumulation." (PMID 41425635, 2025). "PPARα is a vital regulator of lipid metabolism and has been identified as an important therapeutic target for obesity." (PMID 39942052, 2025). "PPARα/δ agonists enhance mitochondrial function and fatty acid oxidation, making them potential treatments for obesity and muscle disorders, including muscular dystrophy and sarcopenia." (PMID 40926269, 2025).
Obesity (continued). "The reduced expression or activity of PPARα and PPARβ/δ in obesity contributes to impaired postprandial lipid clearance, prolonging the elevation of TG-rich lipoproteins after meals." (PMID 41301434, 2025). "The positive effect of Uro-B on PPARα expression has been stated before in high-fat diet-induced obesity in rats." (PMID 40863335, 2025). "The journal retracts the article titled “Lemon Balm Extract ALS-L1023 Regulates Obesity and Improves Insulin Sensitivity via Activation of Hepatic PPARα in High-Fat Diet-Fed Obese C57BL/6J Mice”, cited above." (PMID 39959987, 2025). "Evidence suggests that PPARα and PPARβ/δ are potential therapeutic targets to prevent obesity, while PPARγ, a master regulator of adipogenesis, modulates obesity-related phenotypes." (PMID 41438090, 2025). "Outside the liver, hepatic Rspo3 induction ameliorated reduced skeletal muscle quality in obesity by restoring insulin signaling and up-regulating muscle PPARα expression and muscle fatty acid utilization." (PMID 39854351, 2025). "The knockout studies observed that PPARα in the adipose tissue inhibits lipogenesis and inflammation in diet-induced obesity in a sexually dimorphic way." (PMID 40985048, 2025). "In diet-induced obesity models, PPARα activation upregulates thermogenic genes and energy expenditure, contributing to weight loss." (PMID 41438090, 2025). "Dietary supplementation with phytol has been shown to mitigate obesity and enhance the expression of PPARA target genes, indicating its role in activating PPARA in adipose tissues." (PMID 38732127, 2024). "Here, we demonstrate that Srebp1c, Pparα and Pparγ2 genes reorganize their interactome in obesity to promote a chromatin architecture favoring their transcriptional activation." (PMID 39060446, 2024). "Fibrates, a class of hypolipidemic drugs able to activate peroxisome proliferator-activated receptor α (PPARα), were proven to be an effective treatment for patients with obesity, hyperlipidemia, and NAFLD." (PMID 39086986, 2024). "For instance, AST activates the AMPK pathway and serves as a typical PPARα agonist, enabling it to regulate energy metabolism and promote lipid metabolism in the body, thereby alleviating obesity, hyperglycemia, and dyslipidemia related to MS." (PMID 39852511, 2024). "This study aims to explore if morin supplementation can protect against obesity and hepatic steatosis in a chronic HFD rat model and examine its underlying mechanisms involving PPARα/CPT1 pathways." (PMID 39202687, 2024). "It upregulates fatty acid oxidation genes like Pparα, Acsl, Cpt1, and Cpt2, thereby inhibiting liver inflammation and lipid synthesis while promoting fatty acid oxidation to address obesity induced by a high-fat diet in mice." (PMID 39459158, 2024). "Here we have described the evidence-based selection of suitable chemicals for the development and validation of PPARα and PPARγ as molecular-level events, and white adipose tissue adipogenesis as an apical organ/tissue-level adverse effect for obesity." (PMID 39040675, 2024). "The anti-obesity effects of intestinal PPARα activation were in line with the effects of PPARα agonists administration." (PMID 39807334, 2024). "The peroxisome proliferator-activated receptor alpha (PPARα) is a key anti-obesity factor, regulating metabolism by reducing triglyceride synthesis and promoting fatty acid β-oxidation." (PMID 39202687, 2024). "PPARα agonist prevented obesity in ob/ob obese mice, and pparα absence in ob/ob obese mice, making the mice more obese, suggesting that PPARα protects against obesity in mice." (PMID 38790950, 2024). "Activation of PPARα, a liver-predominant member of the peroxisome proliferator-activated receptors (PPARs), leads to reductions in triglyceride levels, ameliorates obesity, and inhibits liver fatty degeneration, thereby enhancing insulin sensitivity." (PMID 39201413, 2024).
Obesity (continued). "PPARα agonist administration in rodents can also suppress diet-induced obesity and upregulate thermogenic genes in brown adipose tissue." (PMID 39807334, 2024). "It has been reported recently that intestine-specific PPARα-deficient mice fed HFD showed reduced hepatic triglyceride accumulation in the liver and resistance to obesity." (PMID 39064713, 2024). "In the context of obesity, PPARγ facilitates adipose-tissue formation, while PPARα and PPAR-β/δ influence lipid metabolism and metabolic health." (PMID 39766314, 2024). "Bilirubin was recently reported to be a ligand for peroxisome proliferator-activated receptor alpha (PPARα) that induces gene responsiveness, which enhance mitochondrial activity, improves insulin resistance and obesity." (PMID 38843768, 2024). "This suggests that PPARG, PPARA, and other targets should be the primary direct targets for OA to exert its anti-obesity effects." (PMID 38246999, 2024). "As demonstrated in our previous finding that CtBP2 adopts a monomeric state in obese liver due to acyl-CoA deposition, the findings in this study further indicate that CtBP2 represses the transcriptional activity of PPARα particularly in the liver of obesity." (PMID 37286039, 2023). "In conclusion, we identified a novel interaction between CtBP2 and PPARα that responds to metabolic alterations induced by obesity." (PMID 37286039, 2023). "In other words, CtBP2 bound to PPARα on a per molecule basis tended to be increased in mice with genetic obesity (1.6-fold increase based on our densitometric quantification, p = 0.10)." (PMID 37286039, 2023). "In contrast to this physiological regulation of PPARα, there have been several proposed models for the reduced PPARα activity observed in obesity, albeit with some controversy." (PMID 37286039, 2023). "The important role of PPARα and LXRα in lipid metabolism renders them important targets for pharmacological and dietary approaches to improve lipid metabolism, obesity, and metabolic syndrome." (PMID 36903329, 2023). "Our findings demonstrated a sequential event whereby CtBP2 adopts a monomeric configuration in response to obesity-induced metabolic alterations, resulting in binding to PPARα." (PMID 37286039, 2023). "Vegetable oils rich in α-linolenic acid exert anti-obesity effects by inhibiting lipogenesis and the upward regulation of fatty acid β-oxidation via PPARα." (PMID 37958806, 2023). "CGA reduced body weight and fat deposition by possibly involving in PGC-1α and UCP1 in obesity mouse and HepG2 cells and regulating fatty acid β-oxidation by activating PPARα in the liver." (PMID 37710316, 2023). "Altogether, our study strongly indicates that RE improves the lipid profile in animals before the onset of classical signs of obesity, perhaps associated with an increase in fasting GLP-1 or possibly through the upregulation of PPARα and PPARγ." (PMID 37755254, 2023). "For instance, certain citrus fruits or their extracts act as PPARα agonists that exhibit anti-obesity effects via PPARα activation and β-oxidation stimulation." (PMID 38138517, 2023). "The role of PPARα in obesity is well-known; PPARα ligands are clinically used to treat obesity comorbidities such as dyslipidemia." (PMID 38138517, 2023). "The deletion of PPARα was found to promote obesity and steatosis induced by HFD in PPARα knockout mice as compared to the wild-type mice." (PMID 35035496, 2022). "The peroxisome proliferator-activated receptor alpha (PPARα) is the best-known anti-obesity transcription factor in the adipose tissue and liver." (PMID 36615764, 2022). "NK cells express PPARα and PPARβ/δ, and agonists for both PPARs induce a dysfunctional NK cell phenotype; this mimics the NK cell phenotype in obesity, which is unable to exert anti-tumor functions." (PMID 35954274, 2022). "PPARα expression has been demonstrated to increase adiponectin receptor expression and reduce obesity-related inflammation in adipose tissue." (PMID 36005615, 2022).
Obesity (continued). "The data suggest that γ-Oryzanol acts as an anti-obesity, antihyperlipidemic, and anti-adipogenic molecule by stimulating PPARα." (PMID 36615764, 2022). "The PPARα pathway was enriched for placental genes impacted by obesity, and PPARα antagonism significantly reduced 3H-palmitate oxidation in 1st trimester placental explants." (PMID 36371454, 2022). "Consistent with this, we found that the PPARα pathway was significantly impacted in first trimester placentas of women with obesity, suggesting that these changes seen at term begin in the early stages of pregnancy." (PMID 36371454, 2022). "Conversely, when PPARα is suppressed, lipids tend to accumulate in the hepatocytes, further aggravating obesity." (PMID 35328389, 2022). "Further, estrogen potentially inhibits the beneficial effects of PPARα on obesity and lipid metabolism through its effects on PPARα-dependent gene regulation." (PMID 36209101, 2022). "Mouse models are in line with these experimental findings, indicating that whole-body or hepatocyte-specific deletion of PPARα promotes MAFLD in the context of obesity." (PMID 36589809, 2022). "Another study reported that adiponectin activates AMPK and PPARα, which ameliorate obesity and hepatic steatosis." (PMID 35163298, 2022). "Peroxisome proliferator activated receptor alpha (PPARA) functions in lipid metabolism and is of interest because Rlip depletion affects metabolic syndrome, obesity, and insulin resistance." (PMID 35158795, 2022). "Increasing evidence supports a link between PPARα and the incidence of metabolic diseases including diabetes, obesity, dyslipidemia and fatty liver." (PMID 35222033, 2022). "Higher PPARA and PPARG methylation levels were observed in association with obesity, consistent with decreased PPAR-α and PPAR-γ protein expression levels, that lead to dyslipidemia and IR." (PMID 35794109, 2022). "PPARα is known to regulate obesity by increasing hepatic fatty acid activation and decreasing the levels of triglycerides." (PMID 35163298, 2022). "BAT dysfunction has been observed in mouse models of diet-induced obesity where it can be reversed with fenofibrate, a PPARα-agonist." (PMID 35941104, 2022). "Taken together, these results illustrate a mutual interplay between A. muciniphila and PPARα agonism and encourage the application of these bacteria or their components as potential treatment against obesity." (PMID 36430628, 2022). "Similar works showed that a high-fat diet during pregnancy impairs the demethylation of PPARα, therefore inducing lipid metabolism disorders and obesity in offspring." (PMID 36359869, 2022). "Although PPARα activity is known to be increased in obesity- and diabetes-induced cardiomyopathy, the target genes of PPARα are biased in mice fed with HFD." (PMID 35055179, 2022). "In contrast to the well-established roles of PPARα and PPARγ in obesity, diabetes, and NAFLD, little is known about PPAR-β/δ despite its ubiquitous expression." (PMID 33926085, 2021). "This anti-inflammatory effect in the WAT suggests PPARα activation can improve IR and ameliorate obesity." (PMID 33926085, 2021). "Our results demonstrate the first adipose-specific actions for PPARα in protecting against lipogenesis, inflammation, and cholesterol ester accumulation that leads to adipocyte tissue expansion in obesity." (PMID 35011564, 2021). "Mobilized adipocyte fatty acids are oxidized, leading to increased peroxisome proliferator-activated receptor alpha (PPARα)-dependent adiponectin secretion, which in turn increases hepatic fatty acid oxidation to ameliorate obesity-induced fatty liver." (PMID 33758172, 2021). "We previously demonstrated that fenofibrate regulates obesity and lipid metabolism by activating hepatic PPARα actions in obese male low-density lipoprotein receptor-null and female OVX mice." (PMID 33916086, 2021).
Obesity (continued). "Previous reports showed that metabolic reprogramming of NK cells in obesity limits the antitumor responses through different mechanisms, mainly through PPARα/δ pathway and inhibition of mTOR-mediated glycolysis." (PMID 34212054, 2021). "Following 12 months of HF-HS diet, Ppara I-KO mice had reduced adiposity, and improved oral glucose tolerance; hence, intestinal PPARα depletion ameliorated the diet-induced obesity independently of the type and length of the high-caloric diet." (PMID 34857752, 2021). "Taking advantage of these modulatory profiles, diverse studies have pursued CB1R/PPARα dual targeting to tackle obesity." (PMID 33498245, 2021). "A gestational HFD impairs the demethylation of Pparα, thereby inducing obesity in offspring in later life." (PMID 33955677, 2021). "Our results demonstrate the first adipose-specific function for PPARα in protecting against lipogenesis, inflammation, and cholesterol-ester accumulation that leads to adipocyte hypertrophy and obesity." (PMID 35011564, 2021). "The children who were breastfed showed higher expressions of SLC27A2, FASN, PPARα, and INSR, and were at lower risk to develop obesity." (PMID 34073649, 2021). "The PPARα agonist Wy-14,643 directly enhances lipolysis in isolated adipocytes and the suppression of obesity-induced inflammatory cytokines, such as TNF-α and MCP-1 in WAT." (PMID 33926085, 2021). "We previously determined that metabolites associated with obesity activate PPARα signaling to modulate ERα activity in breast cancer cells, while PFAS activate PPARα to affect metabolism and the immune system." (PMID 34836157, 2021). "In an in vivo study, a significant decrease in PPARα and PPARγ mRNA expression levels in adipose tissue was observed after 10 days of exposure to mercuric chloride (HgCl2) in high-fat diet-induced obesity in mice." (PMID 34678938, 2021). "Increasing evidence supports the relation of PPARα and metabolic diseases, including obesity, dyslipidemia, fatty liver and diabetes." (PMID 32127793, 2020). "Taken together, our results show that both hepatocyte-specific and whole-body deletions of Pparα promote obesity, which is dissociated from glucose intolerance in mice housed at thermoneutrality and fed a HFD." (PMID 32300166, 2020). "In the view of above discussion, our results demonstrated that, in guinea pigs, persistent artificial light exposure increased the rate of insulin resistance and obesity by downregulating the AMPKα/PPARα signaling pathway." (PMID 33150187, 2020). "Soy isoflavones prevent obesity and hepatic steatosis by inhibiting mTORC1 via Akt phosphorylation, which results in the downregulation of SREBP1c and the upregulation of PPARα." (PMID 33187321, 2020). "In contrast, in the liver, obesity led to higher expression of Pparα and Pparδ expression in older female livers compared to young females while ADRB3 stimulation led to downregulation of Pparα and Pparδ expression." (PMID 31983693, 2020). "Results of the present study are the first to fully characterize the effects of PPARα/γ dual agonism on macrophage subtypes in adipose tissue during obesity." (PMID 31903139, 2020). "Since the regulation between PPARα and the circadian clock was reciprocal, it was difficult to conclude which one was the up-stream of the other in the development of obesity induced by night light pollution." (PMID 33052228, 2020). "Both metformin and PPARα agonists are well tolerated and commonly used in patients with obesity-related metabolic disorders, such as type 2 diabetes mellitus and hyperlipidemia." (PMID 33177546, 2020). "It is well established that macrophages are an abundant cell type in adipose tissue during obesity and dysmetabolism, so their response to PPARα/γ agonism is potentially important." (PMID 31725756, 2019).